IFNG (interferon gamma)
Diseases named in the same sentence as IFNG in open-access papers (continued):
Sharing a sentence is not in itself a finding about the gene and the disease.
melanoma (continued). "To test this, we performed an interferon gamma (IFN-γ) enzyme-linked immune absorbent spot (ELISpot) using CD8+ T cells isolated from melanoma patients NW-3568 and NW-1751." (PMID 33718594, 2021). "We observed IFNγ deficiency in tumor-specific CTLs isolated from a small number of melanoma and gastric cancer patients." (PMID 32194559, 2020). "A subset of cMet+ CD8+ T cells have been identified in murine tumor models and melanoma patients, where cMet expression is associated with increased cytolytic capacity and effector functions including IFNγ/TNFα and granzyme B/perforin production." (PMID 32545260, 2020). "Recent studies have shown that ∼30% of both melanoma and lung carcinomas have at least one mutation in the IFNγ pathway, including JAK1, IFNGR1, or IFNGR2, and resistance to checkpoint inhibitors in patients is associated with JAK1/2 mutations." (PMID 31133614, 2019). "As expected, M202 melanoma and K562-A2.1 peptide-pulsed cells caused IFNγ release, contrary to mock-pulsed cells and M238 melanoma cells that do not present the peptide." (PMID 31798961, 2019). "Several genetic defects affecting the IFNγ signaling pathway are associated with melanoma resistance to immunotherapy, including checkpoint inhibition." (PMID 29977240, 2018). "It will be a considerable future challenge to identify all mutations associated with IFNγ resistance and to define the coevolution of HLA class I expression in longitudinal melanoma biopsies." (PMID 28561041, 2017). "In this study, the authors show that melanoma patients can become resistant to immunotherapy by acquiring chromosomal alterations and subsequent inactivating mutations in genes of the IFNγ signalling cascade, most often JAK1 or JAK2." (PMID 28561041, 2017). "Here we demonstrate that IFNγ-resistant melanoma clones with inactivating JAK1/JAK2 mutations frequently evolve in patients receiving different types of immunotherapy." (PMID 28561041, 2017). "Assuming that the growth-inhibitory and pro-apoptotic activity of T-cell-derived IFNγ acts selectively on tumour cells, the evolution of genetic variants in melanoma with impaired cytokine signalling was explored." (PMID 28561041, 2017). "Our data demonstrate that JAK1/2 deficiency protects melanoma from anti-tumour IFNγ activity and results in T-cell-resistant HLA class I-negative lesions." (PMID 28561041, 2017). "DCIL-15-based vaccines induced durable Type-1 (i.e. IFNγ-producing) CD8+ T cells reactive against the melanoma-associated Ag TRP2, even in CD4+ T cell-deficient mice." (PMID 25941586, 2014). "We observed that vaccinated WT mice treated with depleting anti-CD8 antibodies as well as mice deficient in IFNγ showed higher melanoma gene expression compared to untreated WT mice." (PMID 24498205, 2014). "While other profiling studies have implicated IFNG pathway (type II interferon) in immune cells, previous melanoma signatures lack the prominent ISG response we describe." (PMID 25314013, 2014). "The prophylactic application of the complex promoted antimetastatic immunity, leading to the autophagy-associated death of melanoma cells via IFNγ/STAT1 activation and attenuated tumor metastasis." (PMID 21931823, 2011). "High NK cell-mediated cytolytic activity against leukemia and melanoma cell lines was associated with a high percentage of CD107a+ NK cells and significant production of IFNγ." (PMID 20169160, 2010). "Furthermore, our data revealed that IFNγ release correlates with the susceptibility of control melanoma cells to NKmK." (PMID 41078003, 2025). "However, the amount of secreted IFNγ varied per melanoma cell line, whereby IFNγ levels during co‐culture correlated with the initial NKmK susceptibility of the four melanoma cell types." (PMID 41078003, 2025). "However, analysis of 45 patient derived melanoma cell lines indicates a trend of high PD-L1 expression in dedifferentiated melanoma cells, associated with broadly enhanced inflammatory signaling upon IFNγ stimulation." (PMID 39736644, 2024).
melanoma (continued). "Similarly, the interferon-gamma (IFN-γ) pathway is known for its role in enhancing antitumor immunity and has been associated with a better prognosis in melanoma patients." (PMID 39916959, 2024). "Ipilimumab, a medication that targets the CTLA-4 protein, was ineffective against melanomas that had deletions (copy number loss) of crucial IFNγ pathway genes including IRF1, IFT1/2, and amplifications (copy number increase) of IFNγ-related pathway inhibitors like SOCS1 and PIAS4." (PMID 37038154, 2023). "It is important to note that some of the mechanisms downstream of IFNγ signaling may be shared between melanoma cells and tumor-associated macrophages." (PMID 36900204, 2023). "We obtained the risk scores of patients with melanoma: risk score = (−0.379123977 × expression of IFNG) + (−0.662084468 × expression of DAPK2) + (0.342818269 × expression of ATG9B) + (0.406559238 × expression of PTK6) + (0.807218069 × expression of BIRC5) + (0.364523721 × expression of EGFR)." (PMID 36690663, 2023). "Collectively, these data show that mutations in the IFNγ pathway could affect immunogenicity in melanoma patients." (PMID 36389735, 2022). "Similarly, an antigen-specific T cell response (IFNγ and lytic enzymes secretion) was induced following stimulation with a melanoma-associated antigen recognized by T cells (MART-1: melanoma antigen recognized by T cells 1) mRNA-loaded CD40-activated B cells." (PMID 34576154, 2021). "In contrast, pro-tumoral effects of IFNγ have been observed in colon carcinoma and melanoma, leading to a loss of IFNγ signaling sensitivity, reduced antigen expression, and induction of key immune suppressive molecules such as indoleamine-2,3-dioxygenase (IDO1) and immune checkpoint proteins." (PMID 35003017, 2021). "We found IFNγ exposures caused melanoma cells escaping from T-cell killing." (PMID 33158915, 2020). "Aberrant DNA hypomethylation and dysregulated chromatin factors partially activated by IFNγ are associated with increased PD-L1 in melanoma promoting resistance to immune checkpoint blockade highlighting the ability of epigenetic mechanisms to encourage resistant phenotypes." (PMID 30850015, 2019). "Interestingly, our data demonstrate that IFNγ-resistant JAK1/2-deficient melanoma cells progress to a ‘higher level' of immunotherapy resistance." (PMID 28561041, 2017). "Allelic JAK1/2 losses predisposing to IFNγ resistance development are frequent in melanoma." (PMID 28561041, 2017). "Indeed, we demonstrated that JAK1/2 loss protected melanoma cells from anti-proliferative and pro-apoptotic IFNγ activity." (PMID 28561041, 2017). "For these experiments, we utilized B16F10 melanoma cells transfected with a minigene encoding the LCMVgp33-41 epitope (B16F10gp33-41), which upregulate surface PD-L1 expression after treatment with IFNγ." (PMID 29050282, 2017). "Finally, using flow cytometry analysis of intracellular IFNγ, we demonstrated that about 40% of TILs reactivity against the melanoma cells is attributable to specific reactivity to the mutated MED15 peptide." (PMID 26819371, 2016). "We developed and validated HLA-A2 flow cytometry, IFNγ real time RT-PCR, and IFNγ ELISPOT assays to monitor specific CD8+ T cell responses in HLA-A2 melanoma patients immunized with genetic vaccines encoding glycoprotein 100 (gp100) or MART-1, two melanoma-associated antigens." (PMID 18945350, 2008). "Consistent with the importance of IFNγ in our model of equilibrium, transcriptomic data from The Cancer Genome Atlas (TCGA) were analyzed, and a positive association was found between IL-12, IFNγ-stimulated gene expression, and increased survival in melanoma patients." (PMID 36881506, 2023). "In order to dissect the mechanism by which PTPN2 acts as an oncogene in melanoma and how its loss correlates with increased sensitivity of tumor cells to immunotherapy, it is important to underline that the tyrosine phosphatase inhibits IFNγ signaling by dephosphorylating STAT1 and JAK1." (PMID 33003469, 2020).
melanoma (continued). "In melanoma, we identified an 8-gene signature (CD28, CD80, CD86, CTLA4, FAS, IFNG, IL10, and IL12A) associated with survival." (PMID 42216340, 2026). "In one melanoma study, IFNγ-induced CD74 overexpression and MIF-CD74 signaling was shown to increase phosphorylated AKT levels, leading to elevated inflammatory cytokine production and promoting disease progression." (PMID 41597203, 2026). "By contrast, conditioned media from IFNγ-treated melanoma cells, which exhibited high levels of kynurenine due to strong IDO1 expression, profoundly inhibited the proliferation of CD4+ as well as CD8+ T cells." (PMID 39962447, 2025). "Importantly, the same signature applied to pre-treatment transcriptomic data from patients with melanoma who subsequently received ICIs, consistently out-performed all other candidate predictive biomarkers tested, including PD-L1 levels, tumor mutational burden, and an IFNγ signature." (PMID 40666515, 2025). "Background/Objectives: Interferon gamma (IFN-γ) in the melanoma tumor microenvironment plays opposing roles, orchestrating both pro-tumorigenic activity and anticancer immune responses." (PMID 39941844, 2025). "To test this, we pretreated melanoma cells with IFNγ alone or in combination with simvastatin (10 μm)." (PMID 41078003, 2025). "Our study revealed that interferon-gamma (IFN-γ), a cytokine that has been shown to stimulate melanoma progression, stimulates the expression of nNOS and COX-2, and subsequently results in the overproduction of NO and PGE2." (PMID 39941844, 2025). "Colocalization of p62, PARP14, and ADPr was also observed in the melanoma cell line A375 following IFNγ treatment (Fig. EV3H), suggesting that this phenomenon is not restricted to lung cells." (PMID 40195501, 2025). "Our previous studies demonstrated that nNOS inhibitors exhibited potent anti-melanoma activity and regulated PD-L1 expressions in the presence of interferon-gamma (IFN-γ)." (PMID 40574005, 2025). "We concluded that IFNγ signaling and, therefore, its secretion plays a pivotal role in melanoma resistance formation during melanoma and NK‐cell interaction, that is, the melanoma tumor microenvironment." (PMID 41078003, 2025). "Consistent with sublethal apoptosis in immune stressed human tumors, treatment of melanoma tumor slices with anti-PD-1, IFNγ and TNF induced caspase-active yet viable tumor cells." (PMID 40166148, 2025). "These cytotoxic T lymphocytes (CTLs) produce interferon-gamma (IFN-γ), which creates an inflammatory environment that can cause melanoma cells to dedifferentiate reversibly." (PMID 40075727, 2025). "Summarized, these data demonstrate the importance of melanoma and NK‐cell interaction, with IFNγ signaling being one of the main signaling pathways mediating the interaction between melanoma and NK‐cells." (PMID 41078003, 2025). "On the other hand, there are studies demonstrating a rather opposite effect, whereby IFNγ leads to a melanoma phenotype switch to a non‐aggressive, less metastasizing phenotype." (PMID 41078003, 2025). "We then tested the ability of MHC1-TIP to capture quantitative changes in antigen presentation, by treating the melanoma A375 cell line with a series of interferon gamma (IFNy) doses ranging from 5 to 100 ng/mL." (PMID 40777321, 2025). "A number of NK‐cell relevant genes were regulated by IFNγ in most of the examined melanoma cell lines." (PMID 41078003, 2025). "Since our findings suggested a possible involvement of CEACAM1 in melanoma resistance formation, we examined its role in the IFNγ‐induced melanoma cell transformation." (PMID 41078003, 2025). "Additional studies demonstrated that IFNγ‐dependent resistance formation is independent from HLA I antigen expression in melanoma but also in K562 chronic myelogenous leukemia (CML) cells." (PMID 41078003, 2025). "Specifically, most of these genes were markedly upregulated following IFNγ exposure in nearly all melanoma cell lines." (PMID 41078003, 2025).
melanoma (continued). "After 24 h co‐culture we determined the secreted IFNγ and found that during co‐culture, all four melanoma cell lines were exposed to IFNγ." (PMID 41078003, 2025). "For instance, a 10-gene IFNγ signature was predictive of response to the PD-1 inhibitor pembrolizumab in patients with advanced melanoma." (PMID 41291768, 2025). "Treatment led to the upregulation of immune-related gene signatures in the TME (IFNγ pathway, CD8 Teff, MHC pathway) and downregulation of melanoma-associated gene signatures after one treatment cycle." (PMID 40993242, 2025). "Like in the KPC model, sgElovl1 pmel-1 T cells infiltrating a melanoma primary tumour were more functional with higher IFNγ production and proliferative potential compared with control T cells." (PMID 40065102, 2025). "We further identified a concentration‐dependent effect of IFNγ on NKmK, with lower IFNγ concentrations inducing reduced resistance formation in 1205Lu melanoma cells." (PMID 41078003, 2025). "Like IL6/STAT3, genetic and pharmacological targeting of GLI1 showed that IFNγ/STAT1 requires functional GLI as a second signal for the full-blown induction of IDO1 in human melanoma cells." (PMID 39962447, 2025). "We established an IFNγ-insensitive model of B16F10 melanoma through CRISPR-Cas9 knockout of IFNγR1 (IFNγRKO)." (PMID 39746898, 2025). "Then, these cells were co-cultured with various human melanoma cell lines and measured IFNγ, TNFα and IL-2 secretion." (PMID 40181966, 2025). "Using mouse models of melanoma, we determine that MBNL loss attenuates MHC Class I antigen presentation, response to immune stimulation by interferon gamma, and subsequent cancer cell killing by cytotoxic T cells." (PMID 40305509, 2025). "For this purpose, we utilized a publicly available RNA‐seq dataset comprising 42 melanoma cell lines before and after IFNγ exposure." (PMID 41078003, 2025). "Concretely, we evaluated the viability of melanoma spheroids (embedded in a collagen matrix) exposed to NK‐cells, either as untreated controls or following IFNγ treatment." (PMID 41078003, 2025). "To this end, we treated 1205Lu and WM793 melanoma cells with either recombinant IFNγ (350 ng·mL−1) or with primary NK‐cells in a co‐culture for 24 h." (PMID 41078003, 2025). "To further examine the link between the influence of recombinant IFNγ treatment and NK‐cell co‐culture in melanoma cells, we determined MHC II protein and gene expression patterns." (PMID 41078003, 2025). "To address this, we extended our study by investigating the impact of IFNγ on melanoma gene expression and identifying potential molecular targets contributing to IFNγ‐induced resistance." (PMID 41078003, 2025). "Next, NK‐cells were added to the melanoma cell culture, with either the IFNγ‐blocking antibody or with an isotype control." (PMID 41078003, 2025). "To assess the impact of Siglec-7-based CSR on T cell function, we first co-cultured engineered T cells with various human melanoma cell lines and measured TNFα, IFNγ and IL-2 secretion." (PMID 40433387, 2025). "By analyzing single‐cell RNA sequencing (scRNA‐seq) patient datasets, we identified IFNγ as a predicted key interactor between melanoma and NK‐cells." (PMID 41078003, 2025). "Clinical evidence demonstrates that PD‐1 pathway blockade effectively inhibits IFNγ signaling in breast cancer, melanoma, and CRC cells, thereby alleviating T cell exhaustion and enhancing CD8+ T lymphocyte‐mediated antitumor immunity." (PMID 40919133, 2025). "We observed a strong reduction of IFNγ production in the co‐culture containing NK‐exposed, that is, resistant melanoma cells as compared to the co‐cultures containing NK‐naïve melanoma cells." (PMID 41078003, 2025). "In melanoma, IFNγ can lead to an epithelial to mesenchymal transition and to a transformation towards an undifferentiated and more invasive melanoma phenotype." (PMID 41078003, 2025).
melanoma (continued). "Our results clearly demonstrated that, like DMF, simvastatin effectively blocks IFNγ‐induced melanoma cell resistance to NKmK." (PMID 41078003, 2025). "Our findings confirmed and further expanded the understanding of IFNγ's role in melanoma cell resistance to NKmK." (PMID 41078003, 2025). "In 3/6 melanoma cell lines significant upregulation of the genes in the IFNG-ICB response signature was also observed upon guadecitabine treatment." (PMID 40682094, 2025). "In line with our observations of IL6-treated cells, genetic inhibition of GLI1 expression strongly reduced IFNγ-mediated transcriptional induction of IDO1 in WM35 melanoma cells as measured by qPCR." (PMID 39962447, 2025). "Several studies have demonstrated that elevated levels of IL2RG as well as genes such as IL2RA, IL7R and IFNγ can promote melanoma metastasis by increasing intratumoral regulatory T cells through activation of the JAK-STAT signaling pathway." (PMID 40096084, 2025). "The results demonstrated that, in the activated state, CM from Vin-treated melanoma cells similarly enhanced the expression of IFNγ, GZMB, IL-2, and TNFα in Jurkat cells." (PMID 40866941, 2025). "Targeting the master regulator CIITA, which governs MHC II expression and is affected by IFNγ, significantly reduced melanoma cell resistance to NKmK." (PMID 41078003, 2025). "Using two different shRNA constructs, we performed RNAi-mediated knockdown of GLI1 in the BRAFV600E mutant human melanoma cell line WM35 treated for 18 h with IFNγ [10 ng/mL]." (PMID 39962447, 2025). "Since we identified IFNγ to induce melanoma resistance formation to NKmK, we proceeded with pharmacological targeting of IFNγ signaling as a tool to reduce the NK‐cell‐induced immune evasion in melanoma cells." (PMID 41078003, 2025). "In patients with stage III melanoma receiving neoadjuvant therapy, baseline intratumoral IFNγ scores also predict responses, with 95% of patients with IFNγ-high tumours achieving a pathological response, compared to 59% in patients with IFNγ-low tumours." (PMID 41291768, 2025). "Specifically, IFNγ signaling leads to ERK overactivation in melanoma cells, followed by the generation of an overstress response that leads to cell death." (PMID 40276062, 2025). "To achieve that, we exposed 1205Lu and WM793 melanoma cells to recombinant IFNγ and tested for their protein and gene expression patterns." (PMID 41078003, 2025). "Accordingly, we next focused on elucidating the contribution of the IFNγ‐CIITA‐MHC II axis on melanoma cell resistance to NKmK." (PMID 41078003, 2025). "Further, there are studies underlining the effects of IFNγ on immune cell recognition, whereby IFNγ was demonstrated to increase MHC I expression in melanoma, inhibiting NK‐cell subsets in their melanoma clearance." (PMID 41078003, 2025). "Compared with IFNGlow patients, melanoma patients treated with pembrolizumab who exhibit high expression of IFNG have increased PFS." (PMID 40108693, 2025). "A multivariable model combining both features predicted response in patients with advanced melanoma, with an area under the curve (AUC) of 0.84, while the IFNγ gene signature alone had an AUC of 0.76." (PMID 41291768, 2025). "FTO overexpression in leukemia can also generate a resistant phenotype against EGFR TKIs, and its downregulation resensitizes melanoma cells to interferon gamma (IFN-γ) and anti-programmed cell death protein 1 (PD1)." (PMID 40722726, 2025). "For this, we applied monoclonal antibodies to block IFNγ activity during NK‐cell–melanoma cell co‐culture (approach 1) or by adding recombinant IFNγ to melanoma cells instead of using primary NK‐cells as a source (approach 2)." (PMID 41078003, 2025). "PARP14 upregulation has been observed in melanoma cell cultures derived from patient tumors resistant to immunotherapy with elevated IFNγ signaling." (PMID 40195501, 2025). "Interferon-gamma (IFN-γ) has two functions in melanoma immunity beyond its role in immune checkpoint regulation." (PMID 41394861, 2025).